ALX4 (ALX homeobox 4)
Diseases named in the same sentence as ALX4 in open-access papers (continued):
Sharing a sentence is not in itself a finding about the gene and the disease.
ALX4 also shares sentences with these, for which no sentence is quoted: hepatocellular carcinoma (3 papers); hypogonadism (3); colon cancer (2); Alopecia universalis (1); autism (1); brain tumor (1); Branchio-oculo-facial syndrome (1); breast tumor (1); Carvajal syndrome (1); Char syndrome (1); cleft lip (1); Colorectal (1); ectodermal dysplasia (1); gastric tumors (1); gastroschisis (1); hypotrichosis 4 (1); hypotrichosis 6 (1); Langer-Giedion syndrome (1); liver cancer (1); melanoma (1); multiple exostoses type II (1); Netherton syndrome (1); Neurodevelopmental delay (1); Obesity (1); odonto-onycho-dermal dysplasia and (1); pure hair and nail ectodermal dysplasia (1); Schöpf-Schulz-Passarge syndrome (1); squamous cell carcinoma (1); type 2 diabetes (1); Umbilical hernia (1).
A further 3 diseases each share a sentence with ALX4 in 1 paper.